CPQ (carboxypeptidase Q)
Description:
Carboxypeptidase that may play an important role in the hydrolysis of circulating peptides. Catalyzes the hydrolysis of dipeptides with unsubstituted terminals into amino acids. May play a role in the liberation of thyroxine hormone from its thyroglobulin (Tg) precursor.
Synonyms: PGCP; LDP
Tractability: Antibody: UniProt places it where antibodies can reach, with high confidence; UniProt predicts a signal peptide or a membrane-spanning region; its Gene Ontology location is reachable by antibodies, with medium confidence. PROTAC: its protein half-life has been measured.
Gene: Protein-coding gene on chromosome 8 (96,645,240 to 97,150,160, forward strand). Ensembl gene ENSG00000104324.
Subcellular location: Endoplasmic reticulum; Golgi apparatus; Lysosome; Secreted
Subcellular location (Human Protein Atlas): Golgi apparatus; Vesicles; Predicted to be secreted
Gene Ontology:
Molecular function: metallodipeptidase activity; protein homodimerization activity
Biological process: peptide catabolic process; proteolysis; thyroid hormone generation; tissue regeneration
Cellular component: cytoplasm; extracellular exosome; extracellular region; Golgi apparatus; endoplasmic reticulum; lysosome
Genetic constraint (gnomAD): Loss-of-function variants: 31 observed, 38.83 expected, observed/expected ratio (o/e) 0.8, 90% interval 0.6 to 1.08. The upper end of that interval is the gene's LOEUF score, 1.08, which puts it in group 4 of 6, group 1 being the genes least tolerant of losing a copy. Missense variants: 480 observed, 538.53 expected, observed/expected ratio (o/e) 0.89, 90% interval 0.83 to 0.96. Synonymous variants: 161 observed, 190.68 expected, observed/expected ratio (o/e) 0.84, 90% interval 0.74 to 0.96.
Homologues: Orthologues: chimpanzee CPQ (99% identical), macaque CPQ (98% identical), pig CPQ (91% identical), dog CPQ (88% identical), mouse Cpq (88% identical), rat Cpq (88% identical), rabbit CPQ (86% identical), guinea pig CPQ (85% identical), tropical clawed frog cpq (71% identical).
Diseases named in the same sentence as CPQ in open-access papers:
CPQ is named in the same sentence as 17 diseases in open-access papers, as found by Europe PMC text mining. Sharing a sentence is not in itself a finding about the gene and the disease. The quoted sentences say what the papers report.
migraine (5 papers, 2014 to 2022). "We have previously replicated the finding of an association for two of the established risk alleles for migraine in a Swedish migraine case-control population, rs2651899 in PRDM16 (PR/SET domain 16) and rs1835740 located between MTDH (metadherin) and PGCP (carboxypeptidase Q) on chromosome 8q22.1." (PMID 30382894, 2018).
Ascites (3 papers, 2018 to 2022). Accumulation of fluid in the peritoneal cavity (between the layers of the peritoneum that lines the abdomen). "To further dissect the role of the gene polymorphisms in association with ascites, we assessed the relationship between the various genotypes/haplotypes and CPQ gene expression in unchallenged, healthy REL line birds." (PMID 29293530, 2018). "Additional genotyping for the LRRTM4 region demonstrates an epistatic interaction with the CPQ region for ascites phenotype." (PMID 32434464, 2020). "Our findings indicate CPQ is an important determinant of pulmonary hypertension syndrome leading to ascites in broilers." (PMID 29293530, 2018). "The region on chromosome 2 for CPQ has already been extensively analyzed for association with ascites phenotype and confirmed for association of the non-reference SNPs with ascites resistance in males." (PMID 32434464, 2020). "Selection based on SNPs in the carboxypeptidase Q (CPQ, Gga2) and leucine rich repeat transmembrane neuronal 4 (LRRTM4, Gga22) gene regions resulted in a sex- and simulated altitude- dependent reduction of ascites incidence in two F2 cohorts of the MAS line." (PMID 35090566, 2022). "Therefore, the current study reports on whether MAS based on SNP genotypes for the regions of both CPQ and LRRTM4 can produce offspring with greater innate ascites resistance." (PMID 35090566, 2022).
Stroke (3 papers, 2021 to 2024). Sudden impairment of blood flow to a part of the brain due to occlusion or rupture of an artery to the brain. "The results showed that 6 genes filtered with optimal lambda value were identified as diagnostic characteristic genes in stroke, namely, HAS3, VIM, ZFP36L2, CPQ, F5, and PIK3CG." (PMID 38649659, 2024). "Specifically, when comparing MCAO vs. sham, proteins FBXO7, WIPI2, NTRK2, A0A0G2JY03, and ITGB8 appeared clearly underexpressed, whereas MAP1a and CPQ were overexpressed, indicating a clear effect of the stroke (MCAO injury) on the individuals." (PMID 35008673, 2021). "After taking the intersection of SCFA metabolism-related genes and the co-expression WGCNA modules of stroke, 10 SCFA-related hub genes were obtained, and 6 of them showed high diagnostic efficacy through LASSO regression and ROC analysis, including HAS3, VIM, ZFP36L2, CPQ, F5, and PIK3CG." (PMID 38649659, 2024). "It suggests that CPQ might be a promising therapeutic target for stroke." (PMID 38649659, 2024).
diabetes (2 papers, 2020 to 2023). "Notably, three proteins (CPQ, CTSB, and GNS) were common among all four urinary signatures, and they were consistently excreted at higher rates in diabetes." (PMID 32453760, 2020).
endometrial cancer (2 papers, 2015 to 2021). Primary or metastatic malignant neoplasm involving the endometrium (mucous membrane that lines the endometrial cavity). "CPQ-PRKDC occurs at a low frequency in endometrial cancer (2.5%, 3/122), and is formed by the rearrangement of exons 1–2 of CPQ and exons 80–87 of PRKDC on chromosome 8." (PMID 34381020, 2021). "We detected only CPQ-PRKDC fusion transcript in three of 122 primary endometrial cancer tissues." (PMID 26689674, 2015). "In endometrial cancers, the CPQ-PRKDC fusion transcript may be a passenger aberration related to gene amplification." (PMID 26689674, 2015). "Similarly, the two endometrial cancer tissues expressing the CPQ-PRKDC fusion transcript also showed relatively lower expression of the CPQ-PRKDC fusion transcript." (PMID 26689674, 2015). "To rule out congenitally inherited gene fusions, we next conducted RT-PCR using paired normal tissues obtained from patients whose endometrial cancer tissues harbored the CPQ-PRKDC fusion transcript, and confirmed that this fusion event was somatic and tumor-specific." (PMID 26689674, 2015). "To assess the frequency of occurrence of the three in-frame kinase fusions (CPQ-PRKDC, VGLL4-PRKG1, CAPZA2-MET) in clinical samples, we conducted RT-PCR and Sanger sequencing for 122 primary endometrial cancer tissues." (PMID 26689674, 2015). "Of particular interest to us was the novel kinase fusion CPQ-PRKDC, which we also detected in 2.5% of primary endometrial cancer samples." (PMID 26689674, 2015). "The expression of the total PRKDC transcript in the CPQ-PRKDC fusion-positive cell line was relatively higher than that in the other endometrial cancer cell lines that did not have the CPQ-PRKDC fusion." (PMID 26689674, 2015).
Abdominal obesity (1 paper, 2024). Excessive fat around the stomach and abdomen. "Conversely, individuals carrying the minor allele (T) of the carboxypeptidase Q (CPQ) rs59465035 gene tend to exhibit reduced susceptibility to abdominal obesity, particularly in cases of higher vitamin C consumption." (PMID 39203810, 2024).
glioblastoma (1 paper, 2025). The most malignant astrocytic tumor (WHO grade IV). "Low CPQ expression and high methylation are linked to better overall survival, indicating CPQ’s potential as a prognostic biomarker in glioblastoma." (PMID 40909272, 2025). "CPQ expression is elevated in glioblastoma tissues and inversely correlated with its methylation level." (PMID 40909272, 2025).
Hypertension (1 paper, 2018). The presence of chronic increased pressure in the systemic arterial system. "Most importantly the CPQ gene has been associated with hypertension, blood pressure, and heart rate, in human GWAS studies." (PMID 29293530, 2018). "In human GWAS the CPQ gene has shown association with hypertension, blood pressure, heart rate, and electrocardiography." (PMID 29293530, 2018). "Although CPQ has been associated with hypertension and blood pressure in humans, the precise role of the CPQ protein in mediating these bodily functions are still unclear." (PMID 29293530, 2018). "Our current findings of an association of CPQ with hypertension in chickens and the possible contribution of relative expression levels for some alleles may inform biomedical investigations on the role of CPQ in human hypertension." (PMID 29293530, 2018).
ischaemic stroke (1 paper, 2022). "Eight hub genes (ADM, ANXA3, CARD6, CPQ, SLC22A4, UBE2S, VIM and ZFP36) were revealed to be significantly correlated with ischaemic stroke by the LASSO logistic regression and SVM-RFE algorithm." (PMID 35962388, 2022). "Eight hub genes (ADM, ANXA3, CARD6, CPQ, SLC22A4, UBE2S, VIM and ZFP36) were revealed to be significantly correlated with ischaemic stroke by a LASSO logistic regression and SVM-RFE machine learning methods." (PMID 35962388, 2022). "The expression levels of the ADM, ANXA3, CARD6, CPQ, SLC22A4 and VIM genes were significantly increased in the ischaemic stroke patients compared with those in the healthy subjects (p < 0.05–0.01)." (PMID 35962388, 2022). "However, the expression levels of the CARD6, CPQ, UBE2S and ZFP36 genes did not significantly differ between the ischaemic stroke patients and normal subjects." (PMID 35962388, 2022).
prostate carcinoma (1 paper, 2015). A carcinoma that arises from epithelial cells of the prostate gland. "The increased levels of several endosomal/lysosomal peptidases (e.g. cathepsin D, carboxypeptidase Q, probable serine carboxypeptidase CPVL, napsin A) in prostate cancer patients urinary exosomes could be related to cancer progression." (PMID 26196085, 2015).
pulmonary hypertension (1 paper, 2018). Increased pressure within the pulmonary circulation due to lung or heart disorder. "The CPQ gene has been associated with pulmonary hypertension in genome-wide association studies in humans." (PMID 29293530, 2018). "Our study indicates that the CPQ gene is also associated with pulmonary hypertension in broilers." (PMID 29293530, 2018).
cancer (3 papers, 2015 to 2022). A tumor composed of atypical neoplastic, often pleomorphic cells that invade other tissues. "The results showed that ITGA5, NDST1, CPQ, ITGB1, PIGK, EOGT, and TSPAN4 had amplifications or deletions in most cancers." (PMID 36405728, 2022).
CPQ also shares sentences with these, for which no sentence is quoted: tumor (5 papers); liver cancer (2); familial hemiplegic migraine (1); hepatocellular carcinoma (1); migraine with aura (1).